BCL11A (BCL11 transcription factor A)
Diseases named in the same sentence as BCL11A in open-access papers (continued):
Sharing a sentence is not in itself a finding about the gene and the disease.
hematological malignancies (15 papers, 2006 to 2025). "As a transcriptional regulator, BCL11A can play a role in hematopoietic diseases through its own mutation or affect other related blood regulatory factors and changes in oncogenes." (PMID 39857257, 2025). "This review provides a comprehensive overview of the role of BCL11A in normal and malignant hematopoiesis, details the hematological disorders associated with its dysregulation and explores the current therapeutic strategies targeting this transcription factor." (PMID 39857257, 2025). "Genes also implicated in blood disorders, including Bcl11a, Nedd4l, and Aspn, with common pathways involved in regulation of blood pressure, protein modifications, transforming growth factor regulation, and negative regulation of developmental pathways were identified." (PMID 34075076, 2021). "BCL11A also may serve as a valuable diagnostic biomarker and therapeutic target for majority of human hematological malignancies, TNBC, and NSCLC." (PMID 31654056, 2019). "Thus, BCL11A is considered as a potential diagnostic biomarker for some hematological malignancies." (PMID 31654056, 2019). "A noble milestone in the field is the FDA approval of Casgevy, the first CRISPR-based cell therapy, which employs CRISPR-Cas9 to edit BCL11A in hematopoietic stem cells for treating hematologic disorders." (PMID 40968311, 2025). "We aim to summarize the functions of BCL11A within the hematopoietic system and related diseases and discuss its feasibility as a therapeutic target for the treatment of hematological disorders." (PMID 39857257, 2025). "Studies have shown that BCL11A plays a vital role in hematological diseases, particularly hematological malignancies." (PMID 39857257, 2025). "BCL11A acts as an oncogene in hematological malignancies, while DNTT plays role in early T-cell differentiation and V(D)J recombination." (PMID 35565298, 2022). "The functions and mechanisms of BCL11A cooperates with these genes in hematological malignancies are still need further research." (PMID 31654056, 2019). "All five genes are essential to myeloid (EHZF), megakaryocytic (FOG1 and FOG2), T-lymphoid (BCL11B) and B-lymphoid (BCL11A) development; three (BCL11A and B, EHZF) have been implicated in hematological malignancy." (PMID 16704730, 2006). "Additionally, it reviews the various blood disorders resulting from abnormal BCL11A activity and the current therapeutic approaches targeting these conditions." (PMID 39857257, 2025). "In addition to identifying BCL11A as a key gene in these hematological diseases, scientists have investigated its interaction with other key factors in the pathogenesis of these diseases." (PMID 39857257, 2025). "BCL11A in malignant hematopoietic diseases and its functions." (PMID 39857257, 2025). "On the other hand, the accessory subunit BCL11A may have oncogenic functions across multiple hematological malignancies in view of its genetic patterns and expression alterations, which will be detailed in later sections." (PMID 36810086, 2023). "BCL11A is an oncogene of different malignant hematological diseases." (PMID 36030436, 2023). "Among the downregulated master regulators, MYB and BCL11A have been related to immune system regulation in hematologic malignancies, suggesting their participation in the maintenance of the hematopoiesis and in the regulation of other downregulated master regulators such as IKZF1." (PMID 32260546, 2020). "Studies indicated BCL11A may be involved in hematological malignancies by blocking cell differentiation, apoptosis, and promoting cell proliferation." (PMID 31654056, 2019). "Another recurrent alteration involving SWI/SNF genes across various hematological malignancies is the gain or amplification of chromosome 2p16.1, which affects both BCL11A and the nearby REL gene, and which can lead to BCL11A overexpression in some cases." (PMID 36810086, 2023).
hematological malignancies (continued). "Medical intervention to downregulate BCL11A expression and then reactivate γ-globin expression is another frontier in the treatment of related hematological diseases; however, it has not been smoothly implemented." (PMID 39857257, 2025).
neurodevelopmental disorder (7 papers, 2016 to 2025). A behavioral and cognitive disorder with onset during the developmental period that involves impaired or aberrant development of intellectual, motor, or social functions. "For instance, dysregulation of Hivep2 and Bcl11a has been implicated in neurodevelopmental disorders and synaptic dysfunction, and our findings suggest their roles extend to mediating neuronal vulnerability in H-I injury." (PMID 40618091, 2025). "A number of pathogenic de novo deletion, loss-of-function, and missense variants impacting BCL11A have been reported in individuals diagnosed with a distinct neurodevelopmental disorder that also displays persistence of HbF." (PMID 34634037, 2021). "Recent studies have identified pathogenic mutations that cause heterozygous loss-of-function of BCL11A and result in a distinct neurodevelopmental disorder that is characterized by persistent HbF expression." (PMID 34634037, 2021). "Rare haploinsufficient mutations in BCL11A cause a neurodevelopmental disorder with elevated fetal hemoglobin levels." (PMID 34634037, 2021). "Here, we describe a comprehensive interrogation of all reported BCL11A missense variants that have been identified through studies of individuals with neurodevelopmental disorders and shown to also result in impaired HbF silencing." (PMID 34634037, 2021). "In turn, rest-induced (down in mice) ARID4B might interact with rest-induced BCL11A (up in mice); both are associated with neurodevelopmental disorders." (PMID 40725218, 2025). "While additional pathogenic BCL11A variants may be discovered, four BCL11A variants have been identified in studies of thousands of individuals with neurodevelopmental disorders." (PMID 34634037, 2021). "Elevated HbF, reported in BCL11A variants and microdeletions, is also observed in hereditary persistence of fetal hemoglobin (HPFH) and ZBTB7A-related neurodevelopmental disorder [OMIM#619769]." (PMID 39448799, 2025). "It links fundamental experimental research with the emerging amount of clinical and genetic data from individuals affected by Bcl11a- and Bcl11b-dependent neurodevelopmental disorders." (PMID 38392344, 2024). "On the contrary to BCL11A, albeit thousands of whole − exome or whole − genome sequencing studies on patients with neurodevelopmental disorders, no inactivating mutations in USP34 or in XPO1 genes have yet been reported in the literature." (PMID 36807877, 2023). "Thus, our work implicates BCL11A haploinsufficiency in neurodevelopmental disorders and defines additional targets regulated by this gene, with broad relevance for our understanding of ID and related syndromes." (PMID 27453576, 2016).
hematological cancers (2 papers, 2017 to 2022). "Chromosomal translocations resulting in BCL11A overexpression are often seen in human B-ALL tumors, and kit is a proto-oncogene and early developmental marker upregulated in many hematopoietic neoplasms." (PMID 28692033, 2017).
infection (2 papers, 2018 to 2021). The state of being infected such as from the introduction of a foreign agent such as serum, vaccine, antigenic substance or organism. "Knockdown of BCL11A was confirmed by qRT-PCR following islet cell infection." (PMID 30242153, 2018).
adenocarcinoma (1 paper, 2013). A common cancer characterized by the presence of malignant glandular cells. "The average intensity of the 10 probes for BCL11A in SCC was 0.35, significantly higher than that in adenocarcinoma (0.03) (t = 5.37, P = 0.0007)." (PMID 23758992, 2013).
BCL11A also shares sentences with these, for which no sentence is quoted: autism (4 papers); colorectal cancer (4); intellectual disability syndrome (4); acne (2); Alzheimer disease (2); attention deficit-hyperactivity disorder (2); epileptic seizures (2); genetic disease (2); T-Cell Lymphoma (2); acute lymphoblastic leukemia (1); autoimmune disease (1); blood cancers (1); bone marrow failure (1); cholangiocarcinoma (1); colon adenocarcinoma (1); colon cancer (1); depression (1); developmental disability (1); diabetic retinopathy (1); Doyne honeycomb degeneration of retina (1); Duchenne muscular dystrophy (1); dyslexia (1); end-stage renal disease (1); Epileptic encephalopathy (1); esophageal carcinoma (1); Fanconi anemia (1); genetic generalized epilepsy (1); haemolytic anaemia (1); hepatocellular carcinoma (1); hydronephrosis (1).
A further 34 diseases each share a sentence with BCL11A in 1 paper.